FOXP3 (forkhead box P3)
Diseases named in the same sentence as FOXP3 in open-access papers (continued):
Sharing a sentence is not in itself a finding about the gene and the disease.
ankylosing spondylitis (5 papers, 2016 to 2025). An autoimmune chronic inflammatory disorder characterized by inflammation in the vertebral joints of the spine and sacroiliac joints. "Moreover, studies indicate Treg functional impairments in ankylosing spondylitis, potentially due to IL-2 deficiencies, reduced STAT5 phosphorylation, decreased FOXP3 expression, and increased CpG methylation in the CNS2 region of the FOXP3 gene." (PMID 39131703, 2024).
Anxiety (5 papers, 2015 to 2025). Intense feelings of nervousness, tension, or panic often arise in response to interpersonal stresses. "Our findings suggest that concurrent anxiety symptoms in early pregnancy may be associated with concentrations of circulating FoxP3+ Tregs and several Treg subpopulations, but not other populations of T-cells, such as cytotoxic or helper T-cells." (PMID 38016492, 2024).
autoimmune gastritis (5 papers, 2014 to 2025). Inflammation of the body fundic mucosa of the stomach. "Ectopic expression of FOXP3 in CD4+ CD25− T cells may endow CD4+ CD25− T cells with a Treg‐like suppressive capability to prevent the development of IBD and autoimmune gastritis." (PMID 33576136, 2021). "Therefore, we determined the methylation status of the Foxp3 TSDR in of H+/K+ ATPase iTregs before and 1 week after transfer into TxA23 mice with ongoing autoimmune gastritis." (PMID 25119105, 2014).
autoimmune myocarditis (5 papers, 2014 to 2022). Autoimmune myocarditis is an autoimmune disease that affects the heart. "It is known that the presence of FoxP3+ cells protect against the development of autoimmune myocarditis in a different model." (PMID 26592184, 2015). "In a mouse model, depleting CD4+CD25+Foxp3+ regulatory T cells (Tregs) leads to severe multi-organ inflammation, and, similar to EAM, to autoimmune myocarditis with high-titers of anti-myosin autoantibodies." (PMID 24586934, 2014).
autoimmune type 1 diabetes (5 papers, 2012 to 2022). Autoimmune disease wherein the body's own immune system attacks and destroys the cells within the pancreas that produce insulin. "It has been reported that SEA can protect against type 1 autoimmune diabetes via increasing Foxp3 expression in a TGF-β-dependent manner, along with upregulating C-type lectins, IL-10, and IL-2 on dendritic cells (DC)." (PMID 36304936, 2022). "Now, emerging evidence suggests that pancreatic-resident forkhead box P3+ Tregs have distinguishable effects on the suppression of over-exuberant immune responses in autoimmune type 1 diabetes (T1D)." (PMID 29033948, 2017).
cardiac hypertrophy (5 papers, 2016 to 2025). "This is supported by a possible protective role of FoxP3 against the development of cardiac hypertrophy." (PMID 33247627, 2021). "Immunohistochemistry and quantitative PCR showed that Foxp3 and its mRNA were expressed in normal myocardium, and myocardial expression of them was decreased markedly in cardiac hypertrophy mice." (PMID 27965581, 2016). "Transcription factor Foxp3 and inflammatory factors are involved in the process of cardiac hypertrophy and pathological remodeling, which provide a new approach for the prevention and treatment of cardiac hypertrophy." (PMID 27965581, 2016). "In conclusion, TP can effectively ameliorate myocardial damage and inhibit cardiac hypertrophy, which is at least partly related to the elevation of Foxp3 expression in cardiomyocytes." (PMID 27965581, 2016). "Triptolide can effectively alleviate myocardial hypertrophy by inhibiting left ventricular remodeling, elevating the myocardial expression of Foxp3, and correcting the imbalance of expression of α-MHC and β-MHC." (PMID 27965581, 2016). "Myocardial expression of transcription factor Foxp3 decreased markedly in isoproterenol-induced cardiac hypertrophy mice compared to those in the control group (p < 0.01)." (PMID 27965581, 2016). "The forkhead/winged helix transcription factor (Fox) p3 can regulate the expression of various genes, and it has been reported that the transfer of Foxp3-positive T cells could ameliorate cardiac hypertrophy and fibrosis." (PMID 27965581, 2016). "Therefore, the aims of the present study were to explore the regulating effect of TP on myocardial hypertrophy and its relation to Foxp3 in vitro and in vivo." (PMID 27965581, 2016). "Triptolide (TP) can elevate the expression of Foxp3, but its effects on cardiac hypertrophy remain unclear." (PMID 27965581, 2016). "Additionally, in recent years, studies have suggested that TP could attenuate cardiac hypertrophy by upregulating FOXP3 expression and ameliorating cardiac fibrosis." (PMID 33013405, 2020). "However, heretofore, it was unclear whether Foxp3 was expressed in cardiomyocytes and whether Foxp3 was able to suppress the development of cardiac hypertrophy." (PMID 27965581, 2016). "Foxp3 can depress the activation of immune cells and their migration to myocardium, reduce the cardiac interstitial inflammatory cell infiltration and the secretion of cytokines, and then ameliorate cardiac hypertrophy and myocardial damage induced by angiotensin II (AngII) or high blood pressure." (PMID 27965581, 2016). "By this mean, up-regulation of Foxp3 could directly inhibit NFAT activity in myocardial cells, which may attenuate the development of myocardial hypertrophy." (PMID 27965581, 2016).
cervical tumors (5 papers, 2015 to 2021). "A higher percentage of cervical tumors occupied by PTPRC+ cells were strongly associated with enhanced tumor-infiltration by Tbet+ cells and Foxp3+ cells." (PMID 33946372, 2021). "Tumor sections from a group of 58 patients with deep normal tissue-invading cervical tumors were stained for the presence of immune cells (CD45), IFNγ-producing cells (Tbet) and regulatory T cells (Foxp3) by immunohistochemistry." (PMID 26357849, 2015). "We performed a pilot study on 13 primary cervical tumor samples, before and after NACT, to phenotype and enumerate tumor-infiltrating T-cell subpopulations using multiplex immunohistochemistry (CD3, CD8, FoxP3, Ki67, and Tbet) and automated co-expression analysis software." (PMID 31616965, 2019).
clear cell renal cell carcinoma (5 papers, 2016 to 2025). "Tumor infiltration of PD1 positive or Foxp3 positive lymphocytes, termed as exhaustive Treg cells, can used as significant prognostic indicators for clear cell renal cell carcinoma (CRCC)." (PMID 27447564, 2016). "However, a positive correlation between CRP level and FOXP3+ cell tumor infiltration has been observed in clear cell renal cell carcinoma (RCC)." (PMID 32316975, 2020). "A phase I/II clinical study targets patients with metastatic clear cell renal cell carcinoma (ccRCC) by treatment with entinostat and high-dose interleukin-2 (IL2) that downregulates forkhead box P3 (Foxp3) expression and function of regulatory T cells (Treg)." (PMID 33117804, 2020).
cognitive deficits (5 papers, 2016 to 2023). "CD4+CD25+Foxp3+ T cells were also elevated in AD patients, which may be related to AD progression, as patients with a mild cognitive impairment (MCI) show lower CD4+CD25+Foxp3+ T-cell activity than AD patients." (PMID 27964740, 2016).
combined immunodeficiency (5 papers, 2011 to 2023). A broad classification of inherited disorders presenting at birth that affect both the cell-mediated and humoral aspects of the immune response. "Conversely, forced expression of Foxp3 in CD25−CD45RBhighCD4+ SP cells transferred into severe combined immunodeficiency (SCID) hosts suppressed exacerbated inflammation." (PMID 26441956, 2015).
dengue (5 papers, 2016 to 2024). "The authors hypothesized that the expression of FOXP3 could be reduced by the presence of these pro-inflammatory cytokines produced by innate immune cells in severe dengue." (PMID 38752787, 2024). "Thus, IL-2 secretion is crucial in dengue-infected patients for the differentiation of naïve CD4+ T cells into regulatory CD4+/CD25high/Foxp3+ T cells." (PMID 38003826, 2023). "Although FOXP-3 expression is not exclusive of the Treg linage, expansion of Treg cells in acute dengue suggests that these cells suppressed the proliferative response of DENV-specific cytotoxic T cells, as what occurred in vitro and in a mouse model." (PMID 35372587, 2022). "A previous report has shown high levels of IL-6, but not IL-12 or Foxp3+ (a marker of regulatory T-cells) cells, in dengue infected liver sections suggesting a critical role for IL-6 in dengue pathogenesis." (PMID 26982706, 2016). "In addition, a correlation of CD4+Foxp3+ Tregs with the outcome of flavivirus infection has been reported; Treg expansion but not absolute level was lower in children with severe dengue disease." (PMID 27439902, 2016). "In this work, we found that patients with dengue did not significantly express T-bet and ROR-γ, but they showed higher expression of GATA-3 and FOXP-3, particularly in patients that worsen to DHF." (PMID 35372587, 2022).
emphysema (5 papers, 2010 to 2025). "Consistent with the immune phenotype results, the frequency of Foxp3+ Il-17-secreting cells were increased in COPD patients and associated with the severity of emphysema." (PMID 35780120, 2022). "Building on this novel definition of nTregs, we revealed that peripheral Foxp3+GARP+ Tregs are progressively reduced whereas Foxp3+GARP− population progressively increased with increasing quartiles of CT emphysema severity in COPD." (PMID 35780120, 2022). "The mice fed FMT and a high-fiber diet showed reduced production of CD4+CD25+Foxp3+ T cells compared with emphysema mice, suggesting a correlation between inflammatory symptoms and Treg cell number." (PMID 32681029, 2020). "In particular, percentages of CD4+ and CD8+ T lymphocytes as well as CD4+CD25+Foxp3+ (i.e., Treg) cells were investigated, since emphysema can lead to an imbalance in lymphocyte subpopulations." (PMID 30409216, 2018). "However, the immuno-suppressive capacity of Foxp3+ Tregs tends to decrease progressively with increasing emphysema severity." (PMID 35780120, 2022). "In addition to the emphysema quartiles, we also analyzed circulating Foxp3+GARP+ Tregs in COPD patients staged using the Global Initiative on Obstructive Lung Disease (GOLD) criteria and compared them with both non-smoker and smoker controls." (PMID 35780120, 2022). "It is of interest to note, IL-17-secreting Tregs, contained within the Foxp3+GARP− population, increased with the severity of emphysema in our study." (PMID 35780120, 2022). "Peripheral Foxp3+GARP+ Tregs are reduced in COPD patients, and this reduction reversely correlates with quartiles of CT emphysema severity in COPD." (PMID 35780120, 2022). "In our study, as the severity of emphysema increased, the frequency of Foxp3+GARP+ gradually decreased, while Foxp3+GARP− continuously increased, suggesting that compromised immunomodulatory capacity and enhanced pro-inflammatory capacity are involved in the pathogenesis of emphysema." (PMID 35780120, 2022). "Meanwhile, the frequencies of Foxp3+GARP− Tregs, which are characteristic of pro-inflammatory cytokine production, are significantly increased in COPD patients, and correlated with increasing quartiles of CT emphysema severity in COPD." (PMID 35780120, 2022).
hepatitis C (5 papers, 2009 to 2024). "This hypothesis is further supported by higher levels of CD4+/CD25+/FoxP3+ Tregs in mice with severe disease, indicating that CD4+/CD25+/FoxP3+ Tregs might reduce virus-specific CD8+ T cell effector function, which has also been demonstrated for hepatitis C virus infections." (PMID 38979428, 2024).
ileitis (5 papers, 2010 to 2019). "Our results indicated that, in a susceptible host, DR3 stimulation increased the frequency of Foxp3+ Tregs; however, contrary to expectations, this phenomenon was associated with significant exacerbated ileitis." (PMID 29545797, 2018). "In the kidney, apoptotic cells, CD3+ and FOXP3+ cells increased upon ileitis induction of hma mice until day 9 p.i.." (PMID 30761129, 2019). "Interestingly, treatment with 4C12 prior to disease manifestation markedly worsened the severity of ileitis in SAMP mice despite an increase in FoxP3+ lymphocytes in mesenteric lymph node (MLN) and small-intestinal lamina propria (LP) cells." (PMID 29545797, 2018). "Despite having FoxP3+ Tregs enriched in MLN and FoxP3 mRNA upregulated in the ileum, 4C12-treated SAMP mice exhibited a more severe ileitis compared with IgG-treated controls." (PMID 29545797, 2018). "Taken together, treatment with Simvastatin, Resveratrol or Curcumin modulates small intestinal immune cell responses during acute ileitis by decreasing CD3+ and MPO7+ cell accumulation but increasing FOXP3+ and Ki-67+ cell numbers." (PMID 21151942, 2010). "Interestingly, FOXP3+ regulatory T cell (Treg) numbers increased in WT, but not TLR-9-/- mice upon ileitis induction (p < 0.001)." (PMID 24932221, 2014).
immune thrombocytopenia (5 papers, 2018 to 2026). "miR-106b-5p induces immune imbalance of Treg/Th17 in immune thrombocytopenic purpura through NR4A3/Foxp3 pathway." (PMID 36980827, 2023). "Additionally, the overexpressed lncRNA MEG3 interacted with miR-125a-5p and suppressed its expression, whereas the downregulation of MEG3 increased the expression of FOXP3 via miR-125a-5p in the CD4+ T cells in immune thrombocytopenic purpura." (PMID 37709486, 2023).
intestinal tumors (5 papers, 2015 to 2026). "In addition, the number of immuno-suppressive, pro-tumorigenic CD4+Foxp3+ Treg cells increased in myeloid Mir34a-deficient intestinal tumors." (PMID 42140945, 2026). "AOM/DSS-treated chimeras with ST2-deficient hematopoietic cells had no alteration in CD4+ T cell frequencies, yet they showed a reduction of CD4+ FOXP3+ Tregs in intestinal tumors." (PMID 31165767, 2019). "Further studies using immunofluorescence confirmed the presence of ST2+ FOXP3+ cells in human intestinal tumors." (PMID 31165767, 2019). "In line with the data from the BM chimera experiments, endoscopic analysis after 8 and 10 weeks revealed fewer and smaller intestinal tumors in St2fl/fl;Foxp3-Cre versus St2+/+;Foxp3-Cre mice." (PMID 31165767, 2019). "Taken together, our results show that Apc/Min+ Foxp3+ Tregs undergo robust expansion in the intestinal tumor microenvironment and these Treg have altered Gata-3 expression that is important for Treg function in vivo." (PMID 26146642, 2015).
ischemia (5 papers, 2018 to 2023). A hypoperfusion of the BLOOD through an organ or tissue caused by a PATHOLOGIC CONSTRICTION or obstruction of its BLOOD VESSELS, or an absence of BLOOD CIRCULATION. "For example, CD4+ FOXP3+ Treg cell delivery has been shown to reduce infarct size and attenuate MI‐induced cardiac remodeling post‐ischemia in mice." (PMID 34612564, 2021). "Study reported that CD4 + T cells (including Foxp3 + Tregs) infiltrated the ischemia injury heart and promote wound healing via favorably monocytes and/or macrophage trafficking and differentiation." (PMID 33906602, 2021).
keloid (5 papers, 2019 to 2025). An irregularly shaped, elevated mark on the skin caused by deposits of excessive amounts of collagen during wound healing. "Macrophages in keloid tissues are highly activated and promote the differentiation of Treg cells through the upregulation of Foxp3 expression, which aligns with our immune infiltration results." (PMID 40487928, 2025). "Foxp3 expression was significantly increased in CD4+ T cells after incubation with keloid-derived macrophages." (PMID 37587491, 2023). "FOXP3+ CD8− memory T cells have decreased IL-10 secretion, resulting in overexuberant but dysregulated T-cell responses in keloids." (PMID 37587491, 2023). "FOXP3+ CD8- memory T cells are also defective with decreased IL-10 secretion, resulting in exuberant but dysregulated T cell responses in keloids." (PMID 37033989, 2023). "In patients with multiple keloid scars, the local infiltration of Tregs was found to be coupled with a reduction in circulating CD4+ CD25high FOXP3+ Tregs." (PMID 37033989, 2023). "Treg markers, FOXP3 and TGFβ1, and T-cell activation measure ICOS, were up-regulated in lesional keloid versus normal skin (P<0.05 for TGFβ1)." (PMID 33329590, 2020). "CD14+ macrophages derived from keloid tissue, which were co-cultured with CD3+ T-lymphocytes from peripheral blood of keloid patients, were potent stimulators of regulatory T cell differentiation by significantly upregulating Foxp3 expression compared to macrophages from normal skin." (PMID 31187196, 2019).
liver cirrhosis (5 papers, 2016 to 2019). "For instance, the target gene of miR-219-5p is the TF FOXP3, which regulates T cell immunity to facilitate the progression of liver cirrhosis." (PMID 28355233, 2017). "FOXP3 is a well-known regulator of immune responses in T cells to promote the progression of liver cirrhosis." (PMID 28355233, 2017). "The transcription factor -/lncRNA- microRNA-mRNA network we uncovered that results in immune-mediated liver cirrhosis is comprised of 5 core microRNAs (e.g., miR-203; miR-219-5p), 3 transcription factors (i.e., FOXP3, ETS1 and FOS) and 7 lncRNAs (e.g., ENTS00000671336, ENST00000575137)." (PMID 28355233, 2017).
nematode infection (5 papers, 2012 to 2021). "Foxp3+ Tregs have been reported to expand in S. ratti and other GI nematode infections, but finding that a proportion of these Tregs are helminth antigen-specific is intriguing and novel." (PMID 34237106, 2021). "Taken together, the available data so far present a mixed picture in terms of the role for FoxP3+ Tregs in GI nematode infection, and this needs to be resolved." (PMID 24942690, 2014). "In murine models of nematode infection, Foxp3+ Tregs expand after application of parasites and correlate with the period of worm survival, but decrease after application of anti-CD25 antibodies that is associated with increased intestinal pathology." (PMID 22440243, 2012). "Potential mediators of suppression in addition to Foxp3+ Treg are IL-10 producing Foxp3− T cells, IL-10 producing regulatory B cells, alternatively activated macrophages, and tolerogenic dendritic cells that have been shown to mediate suppression during nematode infection in several murine systems." (PMID 25255463, 2014). "Using depletion experiments, we show that CD4+Foxp3+ regulatory T cells did not mediate the suppression of Ig response during chronic nematode infection." (PMID 25255463, 2014). "The aim of this study was to characterise the expression of Foxp3 in the normal canine gut of 18 dogs (mean age: 6.03 years), in 16 dogs suffering from IBD (mean age: 5.05 years), and of 6 dogs with intestinal nematode infection (mean age: 0.87 years) using immunohistochemistry." (PMID 22440243, 2012). "It is of note that in other immune conditions, subsets of FoxP3+ Tregs have been identified such as the IL-33 driven ST2+ FoxP3+ Tregs that prolong transplant graft survival 143, and it may be that similar populations require examination in the context of GI nematode infection." (PMID 24942690, 2014). "We provide evidence that suppression of TD response during chronic nematode infection was established by interference with follicular B helper T cell (TFH) induction, independent of Foxp3+ Treg." (PMID 25255463, 2014). "Until today, no investigations of Foxp3 expression in canine idiopathic IBD, nor in canine nematode infections have been available." (PMID 22440243, 2012).